CYLD (CYLD lysine 63 deubiquitinase)
Diseases named in the same sentence as CYLD in open-access papers (continued):
Sharing a sentence is not in itself a finding about the gene and the disease.
tumor predisposition syndromes (1 paper, 2016). "All three tumor predisposition syndromes are autosomal dominant disorders, in which a germline CYLD mutation was inherited, and a second, non-inherited CYLD mutation or loss of heterozygosity (LOH) occurs in cells for tumor formation." (PMID 31093340, 2016).
ulcerative colitis (1 paper, 2022). An inflammatory bowel disease involving the mucosal surface of the large intestine and rectum. "Furthermore, in patients with ulcerative colitis elevated levels of IL-18 inversely correlate with CYLD expression, suggesting that CYLD deubiquitination of NLRP6 could be a new therapeutic approach for treating intestinal inflammation." (PMID 35650327, 2022).
tumor (182 papers, 2007 to 2026). "A piece of convincing evidence supporting NF-κB’s role in tumor development is that loss-of-function mutations in CYLD, which is known for its deubiquitinase activity in inhibiting NF-κB signaling, leads to spontaneous development of skin cancers." (PMID 39996775, 2025). "Recognized as a tumor suppressor, dysregulation in CYLD is also associated with many other types of cancers." (PMID 39996775, 2025). "Of note, 2 BCACs (one lung metastasis and one primary tumour) had biallelic inactivation of CYLD, which is located at 16q12.1, through loss of heterozygosity (LOH) and point mutation." (PMID 40389436, 2025). "The exosomes released by tumor-associated macrophages contain miR-588, which interacts directly with the 3’ untranslated region of CYLD, leading to the suppression of its expression and loss of tumor suppressive function." (PMID 39605891, 2024). "Some patients have mosaic CYLD mutations, which result in the development of unilateral tumours clustered in specific locations." (PMID 39430072, 2024). "Almost 90% of the tumour-predisposing germline mutations in CYLD are truncating, which affect mostly the USP C-terminal catalytic domain." (PMID 37387450, 2023). "The deubiquitinating enzyme Cylindromatosis (CYLD) is a tumor suppressor that was found to be mutated in familiar cylindromatosis, a condition associated with benign skin tumors." (PMID 35634245, 2022). "A growing body of evidence is accumulating to reveal that loss of CYLD expression in tumor tissues is closely associated with malignant transformation and poor prognosis in various malignant tumors." (PMID 36376983, 2022). "CYLD, a tumor suppressor, inhibits NF-κB signaling by cleaving K63-linked ubiquitination of NEMO/IKKγ, thus reducing its stability and averting the IKK complex from phosphorylation of IκB." (PMID 35874839, 2022). "Loss of CYLD stimulates tumor growth in human cylindromatosis by hyperubiquitination of Dvl and enhanced Wnt signal." (PMID 36202787, 2022). "Cylindromatosis (CYLD) is a tumor suppressor identified in patients with cylindromas in whom both CYLD alleles are lost." (PMID 33919439, 2021). "Mucosa associated lymphoma translocation gene 1(MALT1) gene can cause the cleavage of CYLD and promote the proliferation of tumor." (PMID 33827598, 2021). "Genome sequencing efforts have revealed somatic CYLD mutations in several human cancers, in which it acts as a tumor suppressor through its effects on cellular proliferation, apoptosis, migration, and signal transduction." (PMID 33982884, 2021). "TCF7 and CYLD (a tumor suppressor) were both strong predictors of risk of progression to cancer in this study." (PMID 36860910, 2021). "The tumor-suppressing function of CYLD is also supported by the increased oncogenic susceptibility of CYLD-deficient mouse models to proinflammatory and/or genotoxic stress." (PMID 32722292, 2020). "Recent molecular genetic analysis of HPV-positive head and neck SCC has shown the significance of CYLD mutation in HPV-driven neoplasia." (PMID 32461623, 2020). "The results of our study expand the spectrum of the CYLD mutations and provide valuable information for the development of new treatments or prevention of this disfiguring tumor." (PMID 32783365, 2020). "Previous studies, including studies from our group, were able to link loss of CYLD to increased proliferation and invasion in vitro and tumor progression in vivo." (PMID 31591386, 2019). "CYLD is a deubiquitinating enzyme known for its role as a tumor suppressor whose mutation leads to skin appendages tumors and other cancers." (PMID 30631004, 2019). "More importantly, the combination of cisplatin and bortezomib treatment exhibited significant anti-tumor effects on cisplatin resistance caused by CYLD down-regulation in SAS cells." (PMID 31635163, 2019). "CYLD was identified as a tumor suppressor that is mutated in familial cylindromatosis, and it plays important roles in development and tumorigenesis." (PMID 30388174, 2018).
tumor (continued). "CYLD is a tumor suppressor gene, when germline mutated, it can contribute to a rare form of inherited syndrome called the CYLD (cylindromatosis) cutaneous syndrome with clinical manifestation of multiple benign tumors in the head and neck region at early age." (PMID 29933636, 2018). "Patients with germline mutations in a tumour suppressor gene called CYLD develop multiple, disfiguring, hair follicle tumours on the head and neck." (PMID 28270164, 2017). "Ectopic expression of CYLD wild-type gene suppressed C666-1 cell proliferation and anchorage-independent growth on soft agar, while expression of patient-derived CYLD point and truncating mutations resulted in the loss of these tumour-suppressive activities." (PMID 28098136, 2017). "Firstly, the genetic changes in these tumours were limited, with restriction to loss of CYLD being the only detectable change seen." (PMID 28270164, 2017). "Recently, the development of an ointment containing a TRK inhibitor (pegcantratinib — previously CT327 — from Creabilis SA) allowed for the assessment of TRK inhibition in tumours from patients with inherited CYLD mutations." (PMID 28270164, 2017). "Cells from three different primary tumours from two patients undergoing surgical excision, who carried germline mutations in CYLD (c.2460delc), were used." (PMID 26969893, 2016). "How do CYLD germline mutations give rise to “multiple” tumor formation, in particular, in the head and neck region in these patients?" (PMID 31093340, 2016). "Patients with the CYLD cutaneous syndrome inherit one copy of the mutated CYLD gene, while LOH or mutation of the second copy of the CYLD gene occur somatically for tumor formation." (PMID 31093340, 2016). "In these patients, loss of heterozygosity (LOH) at the CYLD locus is seen in 76% of tumours 18, and some of the remaining cases have compound heterozygous changes affecting CYLD5." (PMID 26969893, 2016). "Such an early age onset of multiple tumor formation distinctly in the head and neck region strongly imply a potential critical role of CYLD mutations in promoting head and neck tumorigenesis." (PMID 31093340, 2016). "CYLD was originally characterised as a tumour suppressor that is mutated in hereditary cylindromatosis, and was later found to be downregulated in many other cancers via deletion or transcriptional repression." (PMID 25595906, 2015). "These tumours are rare in the general population, and a histology result should raise the suspicion of a germline CYLD mutation in a young person." (PMID 25737804, 2015). "To determine if this finding was relevant in a human model, we assessed JAG2 expression in CYLD defective tumour lysates, obtained from patients with germline CYLD mutations." (PMID 25565632, 2014). "With regard to malignancies, reduced expression and mutation of CYLD, with tumor-promoting effects, were reported for several cancers including melanoma, T-cell leukemia, hepatocellular carcinoma, and breast cancer." (PMID 25071012, 2014). "Cylindromatosis (also designated as CYLD) is a well-characterized DUB, where mutations in CYLD are reported to cause cylindramotosis implicating CYLD as a tumor suppressor." (PMID 24961988, 2014). "The tumor suppressor CYLD encodes for a deubiquitinase that plays a critical role in the regulation of NF-κB and activation of caspase-8, its activation being regarded as a therapeutic target in the treatment of cancers." (PMID 23702334, 2013). "CYLD was originally identified as a tumor suppressor, loss of which causes a benign human syndrome called cylindromatosis." (PMID 17925880, 2007). "The deubiquitinating enzyme CYLD was initially identified as a tumor suppressor because loss of which causes a benign human tumor called cylindromatosis." (PMID 17925880, 2007).
tumor (continued). "One CYLD-mutant tumor had a missense mutation and a nonsense mutation and is counted in each group." (PMID 32892208, 2021). "And recovery of CYLD decreased EBV- associated tumor growth in vitro and vivo." (PMID 33654169, 2021). "CYLD is a tumor-suppressor gene that encodes a K63 DUB enzyme." (PMID 34201751, 2021). "Therefore in tumor cells, there would either be biallelic genetic loss of CYLD or posttranslational mechanisms to suppress CYLD." (PMID 32024820, 2020). "CYLD acts as a tumour suppressor and is mutated in a range of human cancers." (PMID 32231246, 2020). "Five distinct pathogenic CYLD variants were found in 5 tumors, with 1 in each tumor." (PMID 31085270, 2019). "Moreover, the combination of cisplatin and bortezomib treatment exhibited significant anti-tumor effects on cisplatin resistance caused by CYLD down-regulation in SAS cells." (PMID 31635163, 2019). "Taken together, our results indicated that bortezomib treatment may serve as a potential therapeutic anti-tumor agent against cisplatin resistant OSCC patients with loss of CYLD expression." (PMID 31635163, 2019). "The bortezomib treatment may serve as a potential therapeutic anti-tumor agent against cisplatin resistant OSCC patients with loss of CYLD expression." (PMID 31635163, 2019). "Furthermore, as expected, the combination of cisplatin and bortezomib treatment exhibited significant anti-tumor effects on cisplatin resistance caused by CYLD down-regulation in SAS cells." (PMID 31635163, 2019). "From this analysis, CYLD was found to carry significantly more mutations than expected (Benjamini–Hochberg (BH)-adjusted p-value 0.01), reconfirming its well-established role as an adnexal tumor predisposition gene." (PMID 31101826, 2019). "Patients with rare, germline mutations in CYLD develop multiple primary tumours in the skin." (PMID 28270164, 2017). "Furthermore, recent studies of the mutational landscape in ACC have shown that CYLD is mutated in 4% of these tumours." (PMID 26969893, 2016). "Moreover, CYLD deficiency resulted in chronic production of tumour-promoting cytokines by tumour-associated macrophages leading to more aggressive tumour growth in a syngeneic model of lung cancer." (PMID 27561390, 2016). "It is likely that the loss of this CYLD tumor suppressor gene makes the entire epithelium of the skin highly prone to tumor initiation by chemicals or environmental insults in the “affected site”, skin in this model, thus multiple tumors can develop in this “primed soil”." (PMID 31093340, 2016). "Determination of the frequency of inactivating mutations in 27,836 genes across cancer (COSMIC database) showed that inactivating mutations were significantly enriched in CYLD and that the CYLD mutation spectrum resembled the spectrum of known tumour suppressors." (PMID 27561390, 2016). "This may reflect differences in hair follicle biology between mice and humans, additional hormonal factors for CCS tumour induction in humans, or perhaps the requirement for CYLD deficiency in a specific stem cell in hair follicles that is key for tumour formation." (PMID 37387450, 2023). "Our findings complement the fact that in HCC, miR-362-5p regulates neutrophil function and promotes tumor progression by targeting CYLD." (PMID 40083930, 2025). "A20, CYLD and Cezanne are deubiquitinase genes that inhibit inflammatory response and tumor progression." (PMID 40731796, 2025). "As predicted, CYLD knockout tumor cells displayed up to 173% improved survival over WT controls when challenged by cytotoxic T cells." (PMID 41315176, 2025). "CYLD was reported to be a key modulator of immune responses, inflammation, thymocyte development, B-cell activation, and tumor cell growth." (PMID 40108019, 2025). "To date, genetic profiling of BCAC cases has revealed mutation of PIK3CA, ATM, CYLD and NFKBIA14,23, but given the rarity of this tumour type and the small number of genes profiled, the roles of these mutations in tumour development is unclear." (PMID 40389436, 2025).
tumor (continued). "Cylindromatosis (CYLD) gene knockdown promotes apoptosis resistance, tumor progression, and development." (PMID 40739397, 2025). "CYLD is usually considered to be a tumor suppressor gene that inhibits TRAF6 ubiquitination by binding to P62, thus modulating the entire RANKL/RANK/TRAF6 pathway." (PMID 38254792, 2024). "In this study, we demonstrated that CYLD, a novel deubiquitinating enzyme, impeded PCa development and progression via tumor suppression." (PMID 38246916, 2024). "The CYLD gene, a tumour suppressor that negatively regulates the NF-κB pathway and other cell proliferation and survival pathways, plays a crucial role." (PMID 39430072, 2024). "CYLD is a tumor suppressor, and downregulation of CYLD leads to increased levels of cyclin D and N-cadherin that promote cell proliferation, migration and invasion." (PMID 38672652, 2024). "Pathology reports and tissue blocks were reviewed, and immunohistochemistry (IHC) was performed in order to assess the expressions of CYLD (tumor-suppressor gene) and mTOR, among other markers." (PMID 38929613, 2024). "The tumors volume and weight of 22RV1/CYLD groups was significantly lower than 22RV1/NC group, also the IHC analysis of CYLD and Ki67 in the xenograft tissues confirmed this inhibitory effect of CYLD on tumor growth in vivo." (PMID 38246916, 2024). "Abnormal expression of Cylindromatosis (CYLD), a tumor suppressor molecule, plays an important role in tumor development and treatment." (PMID 38287022, 2024). "The results of this study suggested that CYLD acted as a tumor suppressor gene in PCa and promoted cell ferroptosis through Hippo/YAP signaling." (PMID 38246916, 2024). "Then, we identified that CYLD inhibits class I HDACs activity, which increasing oxidative stress and DNA damage, thereby promoting tumor radiosensitivity." (PMID 38287022, 2024). "Inhibition of miRNA-499-5p can upregulate the tumor suppressor factor CYLD, leading to the promotion of tumor cell apoptosis, inhibition of proliferation, and enhancement of E-cadherin expression." (PMID 38294713, 2024). "To further explore the potential role of CYLD as a tumor suppressor, we assessed CYLD mRNA and protein levels in a panel of DLBCL and MCL cell lines." (PMID 36922488, 2023). "CYLD, a tumor-suppressor gene, can mediate cell death by regulating the expression of the NF-κB prosurvival gene or the ubiquitination status of RIPK139." (PMID 37714937, 2023). "As a tumor suppressor gene, the expression level of CYLD plays a crucial regulatory role in tumorigenesis." (PMID 37176077, 2023). "FC, MFT, and BSS represent overlapping phenotypes resulting from CYLD deletion, underscoring the significance of CYLD as a crucial tumor suppressor." (PMID 37176077, 2023). "IHC analyses showed stronger CDH4, STAT4, and CYLD immunoreactivity in adjacent basal epithelium compared with that in tumor cells (p < 0.001)." (PMID 37393410, 2023). "This underscores CYLD's role as a tumour suppressor regulating two important hallmarks of cancer: cell death and proliferation." (PMID 37387450, 2023). "The complex role of CYLD in cell cycle regulation and how this relates to its tumor suppressive functions remains to be fully elucidated." (PMID 36922488, 2023). "Contrary to the prevailing notion of CYLD as a strict tumor suppressor, it initiates and terminates NF-κB activity by alternating between oncoprotein and tumor suppressor roles, respectively." (PMID 37176077, 2023). "When subjected to cellular stress, K5-Cyld-wt keratinocytes were more prone to apoptosis, supporting CYLD's role as a tumour suppressor." (PMID 37387450, 2023). "In OSCC, down-regulation of CYLD expression significantly enhanced tumor cell invasion through epithelial-mesenchymal transition (EMT)-like changes through promoted transforming growth factor-β (TGF-β) signaling." (PMID 36376983, 2022).